ENSG00000267303 (novel transcript)
Gene: Protein-coding gene on chromosome 19 (10,315,471 to 10,320,678, reverse strand). Ensembl gene ENSG00000267303.
Genetic constraint (gnomAD): Missense variants: 160 observed, 177.07 expected, observed/expected ratio (o/e) 0.9, 90% interval 0.79 to 1.03. Synonymous variants: 89 observed, 78.92 expected, observed/expected ratio (o/e) 1.13, 90% interval 0.95 to 1.35.